ZNF542P (zinc finger protein 542, pseudogene )
Synonyms: ZNF542
Gene: Long non-coding RNA gene on chromosome 19 (56,368,099 to 56,379,828, forward strand). Ensembl gene ENSG00000290720.
Diseases named in the same sentence as ZNF542P in open-access papers:
ZNF542P is named in the same sentence as 1 disease in open-access papers, as found by Europe PMC text mining. Sharing a sentence is not in itself a finding about the gene and the disease. The quoted sentences say what the papers report.
hepatoma (2 papers, 2018 to 2023). "Intracellular cholesterol ester levels upon simvastatin treatment were raised after ZNF542P knocking-down in a human hepatoma cell line." (PMID 37325631, 2023).